MICA (MHC class I polypeptide-related sequence A)
Diseases named in the same sentence as MICA in open-access papers (continued):
Sharing a sentence is not in itself a finding about the gene and the disease.
breast cancer (continued). "MICA shedding played a significant role in the evasion of breast cancer cell lines to γδ T cell killing under hypoxia in our previous study." (PMID 32636849, 2020). "We previously found that while hypoxia activates γδ T cells, at the same time low oxygen serves to downregulate surface expression and/or increase shedding of MICA by breast cancer cell lines leading to less efficient target cell recognition." (PMID 32636849, 2020). "This appeared to be at least in part due to an inverse correlation between NODAL and surface MICA/B expression on breast cancer target lines." (PMID 32636849, 2020). "Previous studies demonstrated that overexpressed miR-20a in colorectal cancer cells, breast cancer cells, and ovarian cancer cells decreases MICA level and sensitivity to immune effector cells." (PMID 32222150, 2020). "Given the well-established association between age and breast cancer risk, we expected both CD56 and MICA presence to decrease with age." (PMID 29090365, 2018). "Breast cancer cell lines express MICA, a ligand for the natural killer group 2, member D (NKG2D) receptor expressed by γδTc and implicated in γδTc cytotoxicity." (PMID 29963058, 2018). "Collectively, these data demonstrate that miR-519a-3p impairs recognition and killing of breast cancer cell by NK cells via direct targeting of MICA and ULBP2 in addition to inhibiting caspase-7-induced apoptosis." (PMID 28771222, 2017). "We next assessed the endogenous expression of miR-17 and MICA/B in seven breast cancer cell lines (BCap37, MDA-MB-231, MDA-MB-468, Hs 578T, SK-BR-3, BT-474 and MCF-7) and two normal breast cell lines (HBL-100 and Hs 578Bst)." (PMID 29029468, 2017). "This notwithstanding, downregulation of MICA/MICB has been observed in stem-like breast cancer cells, due to the altered expression of the oncogenic microRNA miR20a." (PMID 28404796, 2017). "Among all these strategies, increased levels of soluble MICA/B have been described in breast cancer patients as well as overexpression of HLA-E, HLA-G in HER2+ tumors as determined by immunohistochemistry." (PMID 29181007, 2017). "In examining the mechanism whereby resveratrol regulates MICA/B, we discovered a novel c-Myc/miR-17 pathway that governs MICA/B expression in breast cancer." (PMID 29029468, 2017). "In another study, breast cancer cells were shown to have resistance against autologous/allogeneic natural killer cells due to reduced expression of MICA and MICAB (two ligands for the stimulatory receptor NKG2D)." (PMID 28785557, 2017). "To investigate the significance of miR-17 in breast cancer patients, we analyzed the correlations of miR-17 expression with MICA/B expression, disease stage, overall survival and cancer recurrence." (PMID 29029468, 2017). "In conclusion, resveratrol elevated MICA and MICB expression in breast cancer cells by suppressing the c-Myc/miR-17 pathway, thus increasing the susceptibility of breast cancer cells to lysis by NK cells." (PMID 29029468, 2017). "HER2 signaling was shown to downregulate HLA-I and promote MICA and MICB protein expression in breast cancer cell lines in vitro, enhancing their susceptibility to NKG2D-mediated NK cell recognition and elimination." (PMID 29181007, 2017). "NZ28 down-regulated the HSF1 activity and the MICA/B expression on lung and mammary tumor cells, and this correlated with a reduced sensitivity to NK cell-mediated lysis." (PMID 25854583, 2015). "A direct control of MICA by the BCR/ABL oncogene in chronic myelogenous leukemia had been described, while the HER2-HER3 signalling was involved in the regulation of MICA/B expression in breast cancer cell lines." (PMID 26439264, 2015). "Hence, this enhanced killing of the breast cancer cells can clearly be attributed to the recognition of NKG2D ligands such as MICA and MICB on the target cells’ surface by the NKG2D-based NKAR receptor." (PMID 38334638, 2024).
breast cancer (continued). "However, in the setting of colorectal and breast cancers, high NKR ligand MICA/B and ULBP2 expression was associated with a better prognosis for patients." (PMID 36839682, 2023). "Resveratrol has also been reported to elevate the major histocompatibility complex class I chain-related proteins A and B (MICA and MICB) expression in breast cancer cells by suppressing the c-Myc/miR-17 pathway, thus enhancing the susceptibility of breast cancer cells toward NK cells." (PMID 33802331, 2021). "Since NKG2D is also expressed on NKT cells, CD8+ T cells, γδ T cells, and some activated CD4+ T cells, fusion protein MICA-G129R may also attract and activate these cells to fight against breast cancer." (PMID 34077462, 2021). "In addition, miR-519a-3p impaired NK-mediated breast cancer cell cytotoxicity by downregulating the expression of MICA and ULBP2." (PMID 32316552, 2020). "Thus, we have further explored the integral role for NKG2D/MICA in γδTc cytotoxicity against breast cancer cell lines under hypoxia and normoxia." (PMID 29963058, 2018). "The levels of miR-17 and MICA/B were evaluated in 56 clinical breast cancer specimens." (PMID 29029468, 2017). "The activation of MICA-G129R to γδ T cells may benefit the treatment to breast cancer." (PMID 34077462, 2021). "In the current study, we hypothesized that resveratrol could upregulate MICA/B expression (and, in turn, cancer cell lysis by NK cells) by altering miRNA expression, and provided experimental validation for this hypothesis in human breast cancer." (PMID 29029468, 2017). "Ginsenoside Rh2 substantially inhibits breast cancer growth and metastasis by enhancing NK cell cytotoxicity through direct binding to ERp5, thus modulating the NKG2D/MICA signaling axis, and holds potential as a therapeutic agent for breast cancer." (PMID 40303301, 2025). "A flow cytometric analysis was conducted to assess the expression of NKG2DLs, including hULBP-1, hULBP-2-5-6, hULBP-3, MICA, and MICB, in three tumor cell lines: A549 (lung adenocarcinoma), HELA (cervical cancer), and MCF-7 (breast cancer)." (PMID 40076725, 2025). "Recognition of NKG2DLs such as MICA/B and ULBP1-3 by the activating immunoreceptor NKG2D, expressed by NK and cytotoxic T cells, stimulates anti-tumor immunity in breast cancer." (PMID 38612935, 2024). "In our research, we found that circRNF10 enhanced the expression of MICA, the receptor of NKG2D, to regulate NK cell-mediated toxicity by suppressing PI3K/Akt signaling in breast cancer." (PMID 36497344, 2022). "Resveratrol upregulates MICA and MICB through suppressing the c-Myc/miR-17 pathway in breast cancer cells, and it has been shown to increase the cytolysis of breast cancer cells via NK cells." (PMID 35566016, 2022). "RNA sequencing (seq) data indicate that MICA is the NKG2DL that exhibits the highest expression in, from example, lung, colorectal, stomach, liver and breast cancers." (PMID 34394116, 2021). "For instance, calcitriol, the active form of vitamin D, is capable of suppressing miR-320c and miR-520c in breast cancer cells, which in turn upregulated NKG2D ligands MICA/B and unique long 16-binding proteins 1 through 6 (ULBP2) in cancer cells." (PMID 33572626, 2021). "In particular, miRNAs belonging to the miR-17-92 cluster were downregulated by HDACi leading to the upregulation of MICA/B and ULBP2 and enhancing tumor cell lysis by NK in different hepatocarcinoma and breast cancer cell lines." (PMID 32316552, 2020). "Members of the miR-17-92 cluster, miR-20a, miR-20b, miR-93, and miR-106b, downregulated the expression of MICA/B and ULBP2 in breast cancer cell lines, affecting the capacity of NK cells to recognize and eliminate the tumor cells." (PMID 32316552, 2020). "Here, we report that resveratrol upregulated the protein and mRNA expression of MICA and MICB in breast cancer cells, which in turn promoted breast cancer cell lysis by natural killer (NK) cells in vitro and in vivo." (PMID 29029468, 2017).
breast cancer (continued). "MiR-17 expression correlated inversely with MICA and MICB expression and overall survival in two sets of breast cancer specimens." (PMID 29029468, 2017). "This shows that the NKG2D ligands MICA and ULBP2 are crucial for NK cell cytotoxicity against these breast cancer cells." (PMID 28771222, 2017). "Resveratrol treatment increased the surface levels of MICA and MICB on breast cancer cells in a dose-dependent manner." (PMID 29029468, 2017). "Resveratrol thus upregulates MICA and MICB by suppressing the c-Myc/miR-17 pathway in breast cancer cells, and increases the cytolysis of breast cancer cells by NK cells." (PMID 29029468, 2017). "MICA and MICB expression increased or decreased in breast cancer cells transfected with a miR-17 inhibitor or mimic, respectively." (PMID 29029468, 2017). "STAT3 inhibition increased MICA expression in human GBM and breast cancer cell lines as well, and STAT3 was shown to bind directly to a putative STAT-binding site in the MICA promoter." (PMID 27148255, 2016). "High MICA expression is detected on various tumor cells, including non-small cell lung cancer, colon cancer, breast cancer and leukemia, which is consistent with our MR analysis." (PMID 39751938, 2025). "In conclusion, a novel fusion protein MICA-G129R was created and demonstrated able to bind to PRLR-positive breast cancer cells and NK cells, promote the release of granzyme B and IFN-γ by NK cells and enhance the cytotoxicity to PRLR-positive breast cancer cells." (PMID 34077462, 2021). "Meanwhile, SB203580, an inhibitor of p38 MAPK pathway, blocked the increased MICA/B expression of LA-pulsed DCs, and the increased secretion of perforin, granzyme-B, IFN-γ, as well as cytotoxicity of LA/DC-induced NK cells against breast cancer." (PMID 33910591, 2021). "Resveratrol upregulates protein and mRNA expression of major histocompatibility complex class I chain-related proteins A and B (MICA and MICB) in breast cancer cells, which in turn promote breast cancer cell lysis by natural killer (NK) cells in vitro and in vivo." (PMID 34572548, 2021). "We demonstrated that the MICA-G129R fusion protein not only binds to human natural killer NK-92 cells and PRLR-positive human breast cancer T-47D cells, but also promotes NK cells to release granzyme B and IFN-γ and enhances the cytotoxicity of NK cells specifically on PRLR-positive cells." (PMID 34077462, 2021). "We hypothesize that the MICA portion of the fusion protein binds to NKG2D to activate NK cells and the G129R portion binds to PRLR on breast cancer cells, so that the activated NK cells will kill the PRLR-positive breast cancer cells." (PMID 34077462, 2021). "We hypothesized that the fusion protein MICA-G129R will bridge NK cells and PRLR-positive breast cancer cells." (PMID 34077462, 2021). "MICA and MICB expression are regulated by different miRNAs, namely miR-20a, miR-93, miR-520d, miR-106b, and miR-373, with oncogenic functions in several human cancer cells, including prostate, kidney and breast cancer cell lines." (PMID 32316552, 2020). "Besides, it was found that miR-519a-3p undermined the tumor-killing effect of NKs by decreasing MICA and ULBP2 on breast cancer cells." (PMID 32222150, 2020). "However, breast cancer cell lines MCF-7 and MDA-MB231, and prostate cancer cell lines PC-3 were either unresponsive to HC or increased MICA expression." (PMID 32849657, 2020). "In contrast to the reported ADAM10 and ADAM17 activity for MICA/B shedding, MMP14 has been demonstrated to cause MICA shedding in prostate and breast cancer cell lines, independent of ADAM activity." (PMID 33352921, 2020). "Thus, we were surprised that surface expression of MICA/B on MCF-7 and T47D breast cancer lines appeared unaffected by 48 h under hypoxia." (PMID 29963058, 2018).
breast cancer (continued). "Women who were BBD controls (no subsequent breast cancer) did not have statistically different overall tissue values of MICA nor CD56 as compared to BBD cases (patients that later developed cancer)." (PMID 29090365, 2018). "Flow cytometric analysis of MICA/B surface expression on breast cancer lines subjected to 48 h normoxia or hypoxia revealed no significant change in MFI; representative examples are shown for MCF-7 (n = 4) and T47D (n = 2)." (PMID 29963058, 2018). "To determine whether resveratrol could increase the expression of MICA and MICB in breast cancer cells, we exposed BCap37, MDA-MB-231, Hs 578T and MCF-7 cells to 6.25 μM or 25 μM resveratrol for 48 h." (PMID 29029468, 2017). "In our analysis of 56 clinical breast cancer specimens and data from TCGA, it was obvious that miR-17 expression correlated inversely with MICA and MICB expression, potentially indicating that miR-17 inhibited MICA/B expression." (PMID 29029468, 2017). "In addition, MICA and MICB can also be induced by a variety of cell signaling pathways in different cell types; for example, HER2/HER3 signaling regulates the expression of MICA and MICB in human breast cancer cells." (PMID 24885711, 2014). "The fusion protein may be affected by soluble MICA or itself may suppress the NKG2D expression when not bound to breast cancer cells." (PMID 34077462, 2021). "High expression of miR-519a-3p in breast cancer was shown to not only induce the expression of TRAIL and FasL to increase the apoptosis resistance of tumor cells, but also reduced the sensitivity of tumor cells to NK cells by downregulating the expression of the NKG2D ligands ULBP2 and MICA." (PMID 34084160, 2021). "The T-47D cells incubated with MICA-G129R conditioned media showed strong green fluorescence, while the cells with control conditioned media did not, demonstrating that the fusion protein MICA-G129R in the conditioned media binds to PRLR-positive breast cancer T-47D cells." (PMID 34077462, 2021). "We wished to explore the immunosurveillance role of NK cells in premalignant breast tissues by quantitating NK cell infiltrates and an activating marker of early cellular stress, MICA, in benign biopsy tissues from women who did and did not develop subsequent breast cancer." (PMID 29090365, 2018). "Therefore, resveratrol treatment could be a feasible way to improve the MICA and MICB mediated anticancer effects in breast cancer patients." (PMID 29029468, 2017). "However, LA-pulsed DCs pretreated with MICA/B monoclonal antibody could not significantly stimulate the secretion of these effectors by NK cells and the cytotoxicity of NK cells against breast cancer cells." (PMID 33910591, 2021). "Soluble MICA has been shown to down-modulate NKG2D on CD8+ T cells (and presumably also on NK cells, although it was not tested) in breast cancer, working here as a decoy molecule." (PMID 34012432, 2021). "The target cells consisted of two breast cancer cellular lines, MDA-MB468 and SK-BR3, which were analyzed in terms of differential target molecule (EGFR) expression, as well as the presence of non-specific (MICA/B) and specific (CD1d) activating and inhibitory molecules (Fas)." (PMID 40002679, 2025). "Thus, high expression of miR-17, which showed a negative correlation with MICA and MICB levels, might predict a poor prognosis in breast cancer patients." (PMID 29029468, 2017).
multiple myeloma (46 papers, 2014 to 2025). "The high level expression of MHC I molecule MICA on bone marrow myeloma cells renders them highly susceptible to the lysis by natural killer cells." (PMID 38773213, 2024). "The MICA-129Val/Val homozygous genotype has been associated with higher levels of sMICA and the progression of multiple myeloma." (PMID 34208618, 2021). "On the other hand, MICA-129 Val has been associated to an increase in soluble MICA (sMICA) levels in multiple myeloma, which induces NKG2D downregulation and contributes to immune evasion." (PMID 33868281, 2021). "Additionally, other authors observed that IMiDs may enhance the susceptibility of myeloma cells to NK cell-mediated recognition and killing by increasing the expression of MICA and PVR (the ligand for DNAM-1 receptor) in myeloma cells." (PMID 33802806, 2021). "This study investigates how inducing DNA damage in multiple myeloma (MM) cells leads to MICA overexpression, facilitating NKG2D binding on NK cells.We analyzed the relationship between PIM‐2, PARP1, and MM prognosis using public data and clinical samples." (PMID 40557764, 2025). "In conclusion, this study demonstrates that the combination of SMI‐16a and ABT888 enhances NK cell‐mediated tumor killing through the NKG2D/MICA signaling axis, promoting DNA damage and resulting in a stronger antitumor response against multiple myeloma." (PMID 40557764, 2025). "Since tinostamustine upregulated CD38 and MICA/B expression in different myeloma cell lines, we wondered if this effect was translated into an improvement of daratumumab-mediated ADCC." (PMID 38731936, 2024). "In contrast, a miRNA that upregulates MICA expression has also been reported, such as miR-125b, whose upregulation leads to increased MICA levels in human myeloma cells, affecting the immune response against tumors." (PMID 38146340, 2023). "In contrast, as the disease evolves, myeloma cells lose MICA expression and MICA shedding occurs, this latter phenomenon being directly correlated to disease progression." (PMID 33802806, 2021). "Myeloma cells can evade NK cell activity by maintaining human leukocyte antigen (HLA) expression and by shedding MICA, leading to the downregulation or blocking of the NKG2D receptor on NK cells." (PMID 33562441, 2021). "In multiple myeloma cells, CBIs raise the levels of the NK-activating ligands MICA and PVR through cereblon-dependent degradation of IKZF-1/3 and IRF4." (PMID 33411730, 2021). "Initially, myeloma cells are sensitive to the lysis induced by NK cells since they express high levels of the stress-induced self-antigen MICA (the ligand of NKG2D receptor)." (PMID 33802806, 2021). "The shedding of MICA from myeloma cells leads to its increase in the PB, subsequently triggering a downmodulation of NKG2D, which suggests a possible immune escape process." (PMID 33562441, 2021). "Of interest, doxorubicin and melphalan increased both ADAM10 expression and activity on multiple myeloma cells and concomitant release of soluble MICA/B." (PMID 32269567, 2020). "Further, membrane ERp5 was functionally associated with soluble MICA shedding in chronic lymphocytic leukemia patients and enhanced levels of soluble MICA correlated with membrane ERp5 expression in myeloma and lymphoma cells." (PMID 30597841, 2018). "Inhibitors of Hsp90 which are also known to activate HSF1 increase the expression of MICA/B in a variety of multiple myeloma cells." (PMID 25854583, 2015). "Activation of Erk signaling increases the surface expression of MICA in myeloma cells, whereas inhibition of Erk signaling reduces the surface expression of MICA in ovarian tumor cells." (PMID 24885711, 2014). "It was previously reported that VPA enhances NK cell-mediated cytotoxicity in myeloma, ovarian, and liver cancer cells by increasing the expression of MICA and MICB; however, the mechanisms responsible for this effect vary depending on the tumor type." (PMID 24885711, 2014).